FOXP3 (forkhead box P3)
Diseases named in the same sentence as FOXP3 in open-access papers (continued):
Sharing a sentence is not in itself a finding about the gene and the disease.
prostate carcinoma (continued). "We also confirmed that FOXP3 is a direct transcriptional regulator of c-MYC, as described in prostate cancer." (PMID 23888189, 2012). "cKO in FOXP3+ cells in vivo induces elevated levels of proinflammatory cytokines and increase of cytotoxic immune cells (CD8+ T cells, NK cells) in the TME and eradication of solid tumors in mice (BC and prostate cancer models)." (PMID 38698860, 2024). "Double immunofluorescence analysis confirmed that Foxp3+ Tregs expressed CCR4 in the tumor microenvironment, indicating that CCL17–CCR4 axis possibly contributes to the infiltration of Tregs into canine prostate cancer tissues." (PMID 35131860, 2022). "In our study Foxp3+ Tregs were not significantly different in the blood of prostate cancer patients either before or after LDR brachytherapy up to 24 months after RT." (PMID 35804830, 2022). "In addition, while regulatory T cells are typically identified as CD4 + CD25 + FoxP3+ T cells, it has been shown that both CD4 + CD25+ and CD8 + FoxP3+ regulatory T-cell populations can be found within prostate cancer tumors." (PMID 33820953, 2021). "FOXP3 was found to inhibit tumor cell growth, serving as an important repressor for breast cancer oncogene SKP2 and HER2, and FOXP3–miR-146–NF-kB Axis has been suggested in leading to apoptosis during tumor initiation and tumor suppression in prostate cancer." (PMID 28903735, 2017). "First, FOXP3 represses expression of the HER2, Skp2, SATB1 and MYC oncogenes, and induces expression of the tumor suppressor genes p21 and LATS2 in breast and prostate cancer cells." (PMID 24406338, 2014). "It was further noted that miR-146a KO mice and Foxp3cKO mice developed prostatic intraepithelial neoplasia (PIN, a pre-prostate cancerous state), but not prostate cancer, suggesting that miR-146a as well as FOXP3 have a tumor-suppressive role during tumor initiation." (PMID 26682271, 2015). "Mogamulizumab reduced circulating CD4+Foxp3+ Tregs and CCR4+ Tregs but not CD8+ cytotoxic T cells and CD4+ helper T cells in dogs with prostate cancer." (PMID 35131860, 2022). "Immunohistochemistry in serial sections of human tissues showed Foxp3+ and CCR4+ mononuclear lymphoid cells in prostate cancer but not in normal prostate." (PMID 35131860, 2022).
Sepsis (64 papers, 2010 to 2025). Sepsis is defined as life-threatening organ dysfunction caused by a dysregulated host response to infection. "Indeed, a positive correlation was observed between plasma levels of dsDNA and Foxp3 in septic mice, further supporting the association between NETs and Tregs in late sepsis." (PMID 38888975, 2024). "Together, these data suggest that the decrease in CD25+ Foxp3+ Treg in CD43-/- septic hosts may underlie the increased mortality observed in these animals during sepsis." (PMID 30226896, 2018). "In addition, sepsis is associated with an excessive reduction of forkhead box P3 (FOXP3)." (PMID 36562037, 2022). "Recent studies also indicate that the sustained elevation of Foxp3+ Treg proportion in the later stages of sepsis is further influenced by ILC2-M2-mediated promotion of differentiation." (PMID 40806563, 2025). "Implementing FOXP3 reporter mouse models in future investigations would enable precise tracking of Treg differentiation trajectories during sepsis progression, providing critical insights into the plasticity of these immunoregulatory cells." (PMID 40892462, 2025). "Clinical studies demonstrate that sepsis selectively expands forkhead box P3 (Foxp3+) Treg populations while augmenting their inhibitory capacity, with these changes directly correlating with elevated mortality rates." (PMID 40868190, 2025). "By collecting more clinical trial data, we have discovered that in the early stages of sepsis, the proportion of Foxp-3+ Treg cells is the same between the survivor group and the non-survivor group, but the absolute number is higher in the former." (PMID 38339179, 2024). "The significance of the observed increase in IL-10 secretion from Foxp3+ CD8+ T cells during sepsis is based on studies showing that IL-10 can be both beneficial and detrimental to survival during sepsis." (PMID 38633258, 2024). "The results showed that Treg depletion worsened late-stage survival, suggesting a beneficial role of Foxp-3+ Treg cells in severe sepsis." (PMID 38339179, 2024). "On the other hand, in the later stage of sepsis (three days later), the survivor group exhibits an increased absolute count of Foxp-3+ Treg cells, while the proportion is comparatively lower." (PMID 38339179, 2024). "The results showed significantly higher overall expression of Foxp-3 in the severe burn, sepsis, and death groups." (PMID 38339179, 2024). "An intriguing observation is that IL-38 upregulates the number of circulating CD4+/CD25+/FOXP3+ Treg cells in sepsis patients, possibly reflecting the host’s effort to mitigate the cytokine storm in sepsis cases." (PMID 38533512, 2024). "Collectively, these findings described that the RUNX1/FOXP3 axis alleviated immunosuppression in sepsis progression by weakening T and B lymphocyte apoptosis." (PMID 37636994, 2023). "In summary, the RUNX1/FOXP3 axis alleviated immunosuppression in sepsis progression by weakening T and B lymphocyte apoptosis." (PMID 37636994, 2023). "There is growing evidence that CD4 + CD25 + Foxp3 + Tregs play an active role in reducing sepsis-induced inflammation through TGF-β-dependent and TGF-β-independent pathways." (PMID 36816800, 2023). "Further, IL-10 and Foxp3 mRNA levels were also elevated in the cerebral cortex of sepsis survivor mice by the ITK inhibitor." (PMID 37175808, 2023). "Other studies suggest that modulating the suppressive functions of Tregs by silencing Foxp3 would benefit the sepsis model." (PMID 36148230, 2022). "From day 1 to 28 after sepsis diagnosis, both Foxp3 and RORC, the specific transcription factor of Tregs and Th17 cells, respectively, were significantly more highly expressed in survivors than in non-survivors." (PMID 35281010, 2022). "In summary, we conclude that the enhanced expression of MDSCs in DC with sepsis was found to be responsible for suppressing CD4+ T cell functionality as well as expanding the CD4+FOXP3+ Treg activity." (PMID 35720398, 2022).
Sepsis (continued). "Cannabinoids exhibit in vivo protective and anti-inflammatory effects in LPS-induced sepsis and also promote the generation of FOXP3+ Tregs." (PMID 34548620, 2022). "Although these results are contradictory, they do imply that Foxp3+ Tregs play an important role in amending early, late, and even long-term immune disturbances after sepsis." (PMID 35281010, 2022). "To establish the contribution of VISTA+ Tregs to survival in murine sepsis, we chose to adoptively transfer pMSCV-mouse Foxp3-EF1α-GFP-T2A-puro stable Jurkat cells, hereby referred to as Jurkat Tregs, into VISTA-/- mice prior to CLP." (PMID 35401514, 2022). "Ex vivo co-cultured MDSCs and T-cell experiments confirmed and supported the notion that MDSCs suppress T-cell functionality but expand FOXP3+ Tregs in sepsis patients." (PMID 35720398, 2022). "Meanwhile, the proportion of splenic Cd4+Cd25+Foxp3+ Treg continually increased after the onset of sepsis, and proportion of circulating Treg attained the highest level at 72 h." (PMID 35832091, 2022). "In current findings from this study, the expression of Treg cells significantly increased after FP-induced sepsis; nevertheless, decreased FoxP3-labeled cells in FP-induced sepsis and PCP pretreated mice were observed." (PMID 35694296, 2022). "A growing body of evidence shows that CD4+CD25+Foxp3+Tregs play a positive role in alleviating sepsis-induced rapid onset inflammation and improving the outcome of ALI/ARDS through both TGF-β-dependent and independent pathways." (PMID 35281010, 2022). "GM-CSF treatment in sepsis patients significantly decreased MDSCs and FOXP3+ Tregs but increased CD4 T-cell functionality and improved survival." (PMID 35720398, 2022). "It clearly concludes that suppression of the immunosuppressive activity of MDSCs will decrease the expansion of CD4+FOXP3+ cells in sepsis." (PMID 35720398, 2022). "Tregs, which express a unique transcription factor of FOXP3, are vital in maintaining immune tolerance and sepsis balance." (PMID 36162982, 2022). "Our results clearly suggested the benefit of GM-CSF therapy in sepsis patients, as it decreases the MDSCs, FOXP3 expression on CD4+ T cells, and the percentage of apoptotic T cells and increases CD4 T-cell proliferation." (PMID 35720398, 2022). "Treatment of CA septic animals but not PH septic animals with anti-TIGIT mAb significantly reversed sepsis-induced loss of CD4+ T cells, CD8+ T cells, Foxp3+ Treg, and CD19+ B cells in the spleen, which was the result of decreased caspase-3+ apoptotic cells." (PMID 34100383, 2021). "TIGIT was also upregulated on total CD4+ T cells, Foxp3+ Treg, CD4+ Foxp3– Tconv, and NK cells after sepsis in CA mice." (PMID 34100383, 2021). "We additionally analyzed lymphocyte subsets and CD4+ CD25+ forkhead box protein (FoxP3)+ Tregs at admission for sepsis workup as compared to age-matched controls." (PMID 34512621, 2021). "Other biomarkers that can indicate the immune state in sepsis patients include apoptosis markers (Bim, Bid and Bac), caspases, leukocyte markers (HLA-DR, PD-1, FOXP3, CD127) and cytokines (IL-2, IL-6, IL-12, IL-17, IL-22, IL-33, TNF-α, IFN-γ, IL-10 and TGF-β)." (PMID 33336293, 2020). "Along with evidence to support increased levels of Tregs in sepsis patients, there is also evidence to support that expression levels of FOXP3 is enhanced in these patients." (PMID 33336293, 2020). "Secondly, instead of using an anti‐CD25 antibody, the role of conditional Foxp3 knockdown should be examined in a sepsis model under IL‐38 administration." (PMID 31880383, 2020). "In a CLP model of sepsis, it was shown that adenosine is largely responsible for the high expression of FOXP3." (PMID 33336293, 2020). "Another 5–10-month follow-up study in sepsis patients showed an increased frequency of circulating FOXP3+ T cells, along with higher concentrations of IL-33 and IL-10 in their serum when compared to healthy controls." (PMID 33336293, 2020).
Sepsis (continued). "The role of Foxp3+ regulatory T (Treg) cells is ambiguous in the course of the early hyper-inflammatory and subsequent hypo-inflammatory phases of sepsis." (PMID 31191818, 2019). "In this study, we have demonstrated, for the first time, that the HMGB1/PTEN/β-catenin signaling represents a novel regulatory pathway to induce CD4+CD25+Foxp3+ Tregs in sepsis-induced lung injury." (PMID 31402909, 2019). "DEREG mice depleted of Foxp3+ Treg cells exhibit higher inflammation and mortality rates in early-phase sepsis." (PMID 31191818, 2019). "Authors used DEREG (DEpletion of REGulatory T cells) mice model in order to evaluate the role of Foxp3+ Treg cells in the early and late phases of sepsis." (PMID 31191818, 2019). "Taken together, these findings indicate a potential mechanism by which disruption of HMGB1/PTEN axis activates β-catenin signaling and promotes TGF-β, which contributes to the induction of CD4+CD25+Foxp3+ Tregs during lung injury in sepsis." (PMID 31402909, 2019). "Blockade of HMGB1 or macrophage PTEN deletion activates PI3K/PDK1/Akt and β-catenin signaling, which in turn enhances macrophage TGF-β leading to increased Foxp3 Treg induction while inhibiting Th17 cell differentiation during sepsis-induced lung injury." (PMID 31402909, 2019). "Because regulatory T cells are thought to involve in immuno-paralysis in the late phase of sepsis, we have attempted to measure expression of FoxP3 in the CD4 T cells proliferated or skewed by IL-1β." (PMID 31323786, 2019). "Given their known roles in the pathogenesis of both cancer and sepsis individually, interrogating the numbers, phenotypes, and functional changes in Foxp3+ Treg populations in the setting of cancer and sepsis remains an important area of future research." (PMID 29338031, 2018). "It is well documented that the proportion of Foxp3+ Tregs increases during sepsis due to their relative resistance to apoptosis or potential transdifferentiation from Th17 cells into Treg during bacterial infections." (PMID 29415028, 2018). "At 5-10 months after sepsis diagnosis, sepsis survivors have significantly more circulating Foxp3+ Treg cells and also higher concentrations of IL-33 and IL-10 in their serum compared to those of the healthy controls." (PMID 28374774, 2017). "Data presented here show that IL-33/ST2 signalling leads to a significant expansion of Foxp3+ Treg cell population expressing ST2 in sepsis-surviving mice." (PMID 28374774, 2017). "Herein we show that genetic deletion of ST2 and STAT6 prevents the expansion of Foxp3+ Treg cell population in sepsis-surviving mice, concomitant with a marked improvement in the survival rate after secondary pneumonia induced by L. pneumophila infection." (PMID 28374774, 2017). "The frequency and the absolute number of splenic CD4+Foxp3+ Treg cells were marked reduced in Il10−/− sepsis-surviving mice at day 15 after CLP." (PMID 28374774, 2017). "At day 15 after CLP, a significantly higher frequency and an absolute number of CD4+Foxp3+ Treg cells expressing ST2 were found in the spleen of sepsis-surviving mice as compared to naive mice." (PMID 28374774, 2017). "During the early hyper-inflammatory phase of sepsis, specific depletion of Foxp3+ Tregs leads to a more severe course of sepsis with a higher mortality rate and a significantly higher IL-6 level." (PMID 27941849, 2016). "We employed DEREG mice (DEpletion of REGulatory T cells) and a caecal ligation and puncture model to elucidate the role of CD4+Foxp3+ Tregs in sepsis." (PMID 23724126, 2013). "To test how these activated suppressive Foxp3+ Tregs influence the outcome of sepsis, we depleted Tregs from the system before sepsis induction." (PMID 23724126, 2013). "The proportion of CD4+ FOXP3+ T cells is elevated in sepsis patients." (PMID 41158471, 2025).
Sepsis (continued). "This phenotype is similarly seen in patients with prenatal risk factors and presumed sepsis but is modified in patients who will subsequently develop clinical sepsis with a decrease in Treg and T effector frequency, FoxP3 expression, but an increase in activated T cells." (PMID 39072327, 2024). "We first observed that circulating Treg frequencies (CD3+CD4+CD25+CD127-FOXP3+) and expression of Foxp3 in CD3+CD4+CD25+CD127- cells were significantly increased in patients with prenatal risk factors but were not seen if associated with clinical sepsis." (PMID 39072327, 2024). "Because TGF-β is significantly upregulated during sepsis, our results are consistent with the hypothesis that CD28 agonism during sepsis directly increases a population of immunosuppressive CD8+ Foxp3+ T cells." (PMID 38633258, 2024). "Our research was to probe whether RUNX1/FOXP3 axis affects immunosuppression in the process of sepsis by modulating T and B lymphocyte apoptosis." (PMID 37636994, 2023). "We have also shown that in DC patients with sepsis, MDSCs significantly enhanced the expression of FOXP3 on CD4+ T cells and behaved as Tregs, while stimulation with l-NMMA (iNOS inhibitor) and nor-NOHA (inhibitor of Arginase1) significantly suppresses the expansion of Tregs in sepsis patients." (PMID 35720398, 2022). "MDSCs increased FOXP3 expression on CD4+ T cells in sepsis patients (p = 0.006)." (PMID 35720398, 2022). "GM-CSF therapy in sepsis patients leads to a significant decrease in CD4+FOXP3+ Tregs." (PMID 35720398, 2022). "This also suggests that infiltration of macrophages could inhibit lung tissue-specific CD4+CD25+Foxp3+ Tregs via HMGB1/PTEN/β-catenin axis in sepsis-induced ALI." (PMID 35281010, 2022). "There was an increase of Foxp3+ Treg cells to all CD4+ T cells during murine sepsis." (PMID 31191818, 2019). "The increase in CD4 + Foxp3+ and CD8 + Foxp3+ Tregs in vehicle- compared to SBI-425- treated mice is consistent with previous findings which show that elevated Tregs are associated with increased survival and improved sepsis outcomes." (PMID 31827139, 2019). "In sum, our data demonstrate that CD43 deficiency during sepsis results in increased mortality, that may be causally driven by a decrease in CD25+ Foxp3+ Treg populations." (PMID 30226896, 2018). "Further, expansion of TReg cells was associated with T cell anergy in human septic patients, but more mechanistic studies using both loss- and gain-of-function approaches in murine models have revealed that Foxp3+ Treg are likely beneficial in the setting of sepsis." (PMID 30226896, 2018). "While the role of Foxp3+ Treg during sepsis was initially somewhat controversial, the balance of studies published over the last decade have demonstrated that Foxp3+ Treg are likely beneficial during sepsis." (PMID 30226896, 2018). "However, CD1a+ DC derived from sepsis and controls differed strongly with respect to Foxp3 induction in proliferating T cells with a two- to three-fold stronger Foxp3 expression in CD25+ T cells activated by patients DC." (PMID 23071758, 2012). "In sepsis, regulatory effects due to Foxp3+ T cells combined to an abundance of precursors for CD1a−negative DC that induce T cell anergy with production, albeit reduced, of regulatory cytokines, would likely contribute to the immunodepression described in patients." (PMID 23071758, 2012). "Thus, in the previously published study we surmised that CD4+ Foxp3+ IL-10-producing cells could be mechanistically responsible for the observed increase in sepsis survival in CD28 agonist-treated animals." (PMID 38633258, 2024). "Also, FOXP3+ modulatory T cells were necessary for recovery from serious sepsis." (PMID 37636994, 2023). "Furthermore, FOXP3+ regulatory T cells are necessary for recovery from severe sepsis." (PMID 37636994, 2023).